TRPV1 (transient receptor potential cation channel subfamily V member 1)
Diseases named in the same sentence as TRPV1 in open-access papers (continued):
Sharing a sentence is not in itself a finding about the gene and the disease.
cardiac hypertrophy (continued). "Outside of cardiac development, TRPV1 has also been investigated regarding its role in modulating cardiac hypertrophy." (PMID 34867442, 2021). "Some research groups are successfully evaluating a dietary integration of capsaicin, a partial TRPV1 agonist, in mice in order to reduce cardiac hypertrophy and fibrosis and to ameliorate coronary function." (PMID 34564577, 2021). "In a word, dietary capsaicin has protective effects on myocardial hypertrophy and fibrosis in pressure overload mice through TRPV1." (PMID 34040539, 2021). "In conclusion, these data suggest that cold exposure aggravates myocardial hypertrophy and contraction defects induced by pressure overload through TRPV1 and autophagy-dependent mechanisms." (PMID 34040539, 2021). "In rodent models of transverse aortic constriction (TAC), which is employed to induce cardiac pressure overload, thereby cardiac hypertrophy and HF, the role of TRPV1 has intensively been investigated in the last decade." (PMID 32586044, 2020). "A recent study in TRPV1−/− mice showed that transaortic constriction (TAC) surgery enhances the cardiac hypertrophy and cardiac dysfunction in TRPV1-KO mice compared to their wild-type TAC mice." (PMID 31312143, 2019). "Special attention has been given to TRPC’s role in cardiac hypertrophy, but the implication of TRPV1, TRPV2, and TRPM4 has been also demonstrated." (PMID 30881310, 2019). "The present study demonstrates for the first time that chronic TRPV1 activation induced PPAR-δ expression to counteract high-salt-induced cardiac hypertrophy." (PMID 25152753, 2014). "Major findings of the present study show that dietary capsaicin consumption attenuates high-salt-induced cardiac hypertrophy through TRPV1 activation in myocardium." (PMID 25152753, 2014). "The involvement of TRPV1 in pathological cardiac hypertrophy has attracted considerable attention." (PMID 41583526, 2026). "Similarly, dietary capsaicin consumption selectively mitigated long-term high-salt diet-induced cardiac hypertrophy and fibrosis in TRPV1-expressing mice." (PMID 40149710, 2025). "Therefore, TRPV1 contributes to the anti-inflammatory process by inhibiting pressure overload-induced myocardial hypertrophy and exerting cardioprotective effects." (PMID 36045746, 2022). "Moreover, the expression of TRPV1 was upregulated in WT mice with myocardial hypertrophy after surgery, and the cardiac function was worse than that in mice without functional TRPV1." (PMID 34040539, 2021). "Therefore, it is crucial to understand the role of TRPV1 to treat pathological cardiac hypertrophy and other diseases using the current TRPV1 agonist or antagonist available in the pharmacopoeia." (PMID 34564577, 2021). "Therefore, in this review, we aim to discuss the current research on the role of TRPV1 in pathological myocardial hypertrophy to provide a reference for the development of drugs for the treatment of pathological hypertrophy in the future." (PMID 34040539, 2021). "Therefore, it is crucial to understand the role of TRPV1 so that medical professionals can use the existing and unique TRPV1 agonist or antagonist pharmacopoeia to treat pathological cardiac hypertrophy and other diseases." (PMID 34040539, 2021). "Moreover, one study has shown that Ca2+ CaMKII is involved in the activation of TRPV1-induced cardiac hypertrophy." (PMID 34040539, 2021). "A link between TRPV1 and myocardial hypertrophy in mice was also proven." (PMID 34040539, 2021). "And they also considered that a TRPV1 antagonist might provide a new treatment strategy for cardiac hypertrophy and heart failure." (PMID 34040539, 2021). "In CFs from TRPV1 over-expressing mice the sustained Ca2+ rise provoked by capsaicin is enhanced; additionally, in those mice the Isoproterenol-induced cardiac fibrosis and cardiac hypertrophy in vivo are reduced." (PMID 32013125, 2020).
cardiac hypertrophy (continued). "However, 4 weeks after TAC-induced ventricular hypertrophy, TRPV1−/− mice had significantly decreased LV ejection fraction (EF) and fractional shortening (FS) as well as significantly increased secretion of pro-inflammatory cytokines, TNFα and IL-6." (PMID 32586044, 2020). "An early study revealed that TRPV1 knockout mice showed a reduced increase in heart’s weight as compared to wild-type mice, and they were partially protected from pressure-overload induced cardiac hypertrophy." (PMID 30881310, 2019). "However, Trpv1 gene’s deletion was associated with excessive inflammation, exaggerated cardiac hypertrophy, and abnormal cardiac function after TAC, suggesting a protective role of TRPV1." (PMID 30881310, 2019). "It has been reported that increasing TRPV1 channel expression was involved in cardiac hypertrophy." (PMID 30299584, 2018). "In the heart, TRPV1 activation blunted cardiac hypertrophy and fibrosis." (PMID 27120617, 2016). "Interestingly, It has been suggested that Chronic dietary capsaicin could activate TRPV1 to restore Complex I function then up-regulating Sirt3 expression to reverse cardiac hypertrophy." (PMID 39266965, 2024). "Paradoxically, TRPV1 activation restores the ER–mitochondrial tethering by increasing the expression of a MAM protein named phosphofurin acidic cluster sorting protein-2 (PACS2) in pulmonary fibrosis or else favors MAM formation through the AMPK-MFN2 pathway in response to myocardial hypertrophy." (PMID 37759544, 2023). "Importantly, TRPV1 has also been identified as the regulated molecular component of the atrial natriuretic signaling pathway and as a potential molecular target in HF and cardiac hypertrophy induced by TAC in mice." (PMID 32586044, 2020). "However, it remains unknown whether chronic activation of TRPV1 via dietary capsaicin could attenuate cardiac hypertrophy induced by long-term high-salt diet." (PMID 25152753, 2014). "However, it remains unknown whether activation of TRPV1 could alleviate cardiac hypertrophy and fibrosis and the effect of cross-talk between TRPV1 and PPAR-δ on suppressing high-salt diet-generated oxidative stress." (PMID 25152753, 2014). "The subcutaneous administration of the TRPV1 inhibitor, BCTC (4-(3-Chloro-2-pyridinyl)-N-[4-(1,1-dimethylethyl)phenyl]-1-piperazinecarboxamide), reduced cardiac hypertrophy and HF in vivo." (PMID 40149710, 2025). "After long-term capsaicin intervention, WT mice show reduction in high-salt-induced cardiac insufficiency and cardiac hypertrophy; however, these symptoms are not improved in TRPV1-/- mice." (PMID 36045746, 2022). "The results suggest that the absence of TRPV1 or TRPV1 antagonists can prevent or alleviate pathological cardiac hypertrophy." (PMID 34040539, 2021). "Some studies have proven that TRPV1 has an important relationship with pathological myocardial hypertrophy, but the specific mechanism and effect are not clear." (PMID 34040539, 2021). "Mice lacking functional TRPV1 developed significantly reduced cardiac hypertrophy induced by TAC measured over time until 8 weeks after TAC." (PMID 32586044, 2020). "Moreover, TRPV2 and TRPA1 seem to be involved in insulin secretion, TRPV1 and TRPV2 in heart hypertrophy, TRPV3 in skin disorders, TRPV1 and TRPA1 in airway irritation and cough, and TRPV1, TRPV2 and TRPA1 in cancer." (PMID 28333079, 2017). "Thus, it is worth noting that the effects of TRPV1 activation on cardiac hypertrophy have not yet been completely established, and more studies are needed to understand this issue." (PMID 39339783, 2024). "In addition, recent evidence showed that several transient receptor potential channels (TRP), including TRPV1 and TRPC3, are involved in high-salt intake–induced cardiac hypertrophy by mediating mitochondrial function via regulating mitochondrial calcium uptake." (PMID 33996809, 2021).
cardiac hypertrophy (continued). "Furthermore, it has been shown that TRPV1-mediated Ca2+ signals recruit cardioprotective signaling pathways in several mouse models of AMI and HF, whereas the genetic deletion of TRPV1 exacerbated cardiac hypertrophy, myocardial inflammation and fibrosis in a mouse model of TAC." (PMID 40149710, 2025). "Therefore, we should discuss whether TRPV1 and TRPA1 also contribute to cardiac hypertrophy." (PMID 30299584, 2018). "TRPV1 has been found to be upregulated in TAC-induced pressure overload, and mice without functional TRPV1 exhibited reduced cardiac hypertrophy." (PMID 34867442, 2021). "Conversely, pressure overload-mediated cardiac hypertrophy is inhibited in mice lacking TRPV-128, and treatment with a TRPV-1 antagonist prevents cardiac dysfunction in a cardiac hypertrophy model." (PMID 26888607, 2016). "In our experiment, we could not exclude the damage effect of TRPV1 and TRPA1 activation on cardiac hypertrophy when ruthenium red and carvacrol were applied in vivo or in vitro." (PMID 30299584, 2018).
neuropathic pain (27 papers, 2011 to 2025). Chronic pain caused by damage to nerve fibers. "It was shown that neuropathic pain patients with preserved sensory function carrying TRPV1 1911A<G variants (I585V, rs8065080) were protected to develop heat hyperalgesia." (PMID 28817717, 2017). "It has been proposed that D5W relieves pain through a sensorineural mechanism by downregulating transient receptor potential vanilloid receptor 1 (TRPV-1), which is often upregulated in cases of chronic neuropathic pain." (PMID 38392587, 2024). "The main limitation of the current research indicated that microglial and TRPV1 signaling pathways were merely perceived in the SNI-induced neuropathic pain mice model." (PMID 38339048, 2024). "In conclusion, through this study, we have demonstrated the dose-dependent analgesic effect of P.Radix extracts and its spinal TRPV1-modulating effects on paclitaxel-induced neuropathic pain in mice." (PMID 38005716, 2023). "Taking this into account, three compounds 3, 6, and 9, for which affinity for calcium, sodium, and TRPV1 channels had been previously confirmed, were examined to establish their antiallodynic efficacy in the oxaliplatin-induced neuropathic pain model." (PMID 35409413, 2022). "To further strengthen the participation of the spinal TRPV1/TRPM8/P2Y receptors in the development of VCR-induced neuropathic pain, we measured the protein expression of the TRPV1/TRPM8/P2Y receptors using immunohistochemistry." (PMID 34199936, 2021). "These behavioral results demonstrated that the upregulation of TRPV1 contributes to the development and maintenance of neuropathic pain." (PMID 31582966, 2019). "Our findings show the involvement of both TRPA1 and TRPV1 channels in trigeminal neuropathic pain, and in particular, in trigeminal mechanical allodynia." (PMID 30366396, 2018). "In patients with neuropathic pain (NP), TRPV1 is expressed through the nociceptive pathway, from unmyelinated axons in the skin to the back of the spinal cord." (PMID 28321335, 2017). "Constant stimulation of the TRPV1 channel potentially leads to an adjustment of the channel’s conformation/morphology e.g. in neuropathic pain patients." (PMID 28817717, 2017). "Despite these findings in neuropathic pain patients the functional consequence of TRPV1 1911A>G, in healthy subjects, remains to be investigated." (PMID 28817717, 2017). "TRPV1 is a heat sensor and contributes to the sensitisation of peripheral nociceptors in neuropathic pain." (PMID 21468319, 2011). "Thus, targeting TRPV1+ afferents using topical capsaicin is a promising approach to treating neuropathic pain, especially in patients whose hyperalgesia is likely maintained by sensitized nociceptors." (PMID 32404326, 2020). "Taken together, Pirt together with TRPV1 is involved in CCI-induced neuropathic pain." (PMID 29808083, 2018). "TRPV1 is expressed in primary sensory neurons, where its activation results in the perception of pain; therefore, inhibition or desensitization of TRPV1 is thought to be a therapeutic strategy for neuropathic pain." (PMID 27606946, 2016). "Functional knockdown of TRPV1 using shRNA showed diminished behavioral responses to intraplantar injection of capsaicin, enhanced paw withdrawal latencies to heat, and diminished tactile hypersensitivity in an injury-induced neuropathic pain model." (PMID 23305398, 2013). "In the current study, we investigated the changes of p-PKC, TRPV1, SP, and CGRP protein in DRG and SCDH in STZ-induced neuropathic pain." (PMID 36777630, 2023). "Several lines of evidence indicated that the TRP channels i.e., vanilloid 1 (TRPV1) and melastatin 8 (TRPM8) play a pivotal role in chemotherapy-induced neuropathic pain." (PMID 34199936, 2021). "In conclusion, this study reported an interesting role of CBD in the modulation of serotonergic transmission and its antinociceptive and anxiolytic effects mediated by TRPV1 and 5-HT1A receptors in a model of neuropathic pain." (PMID 32766463, 2019).
neuropathic pain (continued). "Our results suggest that TRPM8 and TRPM8-mediated membrane depolarization, but not TRPA1 or TRPV1, serve as the initial ionic/membrane drives that contribute to the development of oxaliplatin-induced neuropathic pain." (PMID 34149356, 2021). "Pretreatment and posttreatment of TRPV1 siRNA via DRG microinjection blocked the development of CCI-induced neuropathic pain and reversed the mechanical allodynia and thermal hyperalgesia in the maintenance phase of neuropathic pain." (PMID 31582966, 2019). "The question here is why did the lack of inputs mediated by TRPV1-expressing C-fibers, which had no influence on allodynia, have an inhibitory influence on the processes involved in synaptic potentiation in the LPB-CeC synapse in the animals with neuropathic pain?" (PMID 22776418, 2012).
irritable bowel syndrome (24 papers, 2010 to 2025). Irritable bowel syndrome (IBS) is a chronic functional condition of the lower gastrointestinal (GI) tract characterized by abdominal pain or discomfort and disordered bowel habit (diarrhea, constipation, or fluctuation between the two). "TRPV1-mediated signaling within the GI tract is involved in the mediation of visceral sensation, motility, and mucosa protective functions; thus, ECS–TRPV1 dysfunction is implicated in both chronic pain syndromes as well as irritable bowel syndrome." (PMID 41303613, 2025). "TRPV1 has been implicated in the pain sensation in various gastrointestinal disorders, including gastroesophageal reflux disease and irritable bowel syndrome." (PMID 33251043, 2020). "TRPV1 is upregulated and sensitized during inflammation episodes and its mucosal expression has been found to be linked with pain severity related to functional disorders including irritable bowel syndrome, and quiescent ulcerative colitis and Crohn’s disease." (PMID 32947778, 2020). "TRPV1 influences pain management and immune modulation in cancer, making it a promising therapeutic target in conditions like irritable bowel syndrome, where TRPV1-expressing sensory fibers correlate with heightened pain perception." (PMID 39407657, 2024). "Other research team found RvD1 displayed potent analgesic properties in irritable bowel syndrome by inhibiting TRPV1 sensitisation." (PMID 36993950, 2023). "The studies from the last two decades indicate that TRPV1 are involved in visceral hypersensitivity in the GI tract and pathogenesis of irritable bowel syndrome (IBS)." (PMID 32002574, 2020). "This is true for patients with irritable bowel syndrome in which the increased density of TRPV1 in the rectosigmoid colon correlates with pain severity." (PMID 21420431, 2011). "Also, the density of TRPV1-positive nerve fibers in the rectosigmoid colon correlates with pain severity in patients with irritable bowel syndrome." (PMID 27322240, 2016). "Furthermore, several studies have reported elevated expression of TRPV1-IR nerve fibers in large intestine biopsies from patients with irritable bowel syndrome and painful Crohn’s disease, Hirschprung disease, rectal hypersensitivity and fecal urgency." (PMID 27322240, 2016). "Studies of biopsies from patients with Irritable Bowel Syndrome show that mucosal fibres containing TRPV1 are increased and that this increase may correlate with symptoms." (PMID 27713376, 2010). "Transient Receptor Potential Vanilloid 1 (TRPV1) channels, which are overexpressed in patients with irritable bowel syndrome (IBS), regulate transmembrane cation flow according to electrochemical gradients, causing increased intracellular Ca2+ and Na+ and subsequent depolarization." (PMID 41155589, 2025). "SiNiSan, a well-known ancient Chinese herbal in the current clinical treatment of irritable bowel syndrome, acts through multiple targets: ADRA2A, HTR2A, F2RL1, F2RL3, PKC, PKA, IL-1Β, NGF, and TRPV1." (PMID 37446251, 2023). "In irritable bowel syndrome (IBS), abdominal pain is a common and distressing symptom where the administration of TRPV1 inhibitors was effective in reducing pain responses to colorectal distension." (PMID 24288041, 2011). "And compared to control rats and enteric glial cells, the expression levels of GFAP, S100B, SP, CGRP, TRPV1, TNF, IL-1β, and IL-6, were significantly higher in the colonic tissues of irritable bowel syndrome (IBS) rats and lipopolysaccharide (LPS)-treated EGCs." (PMID 40225339, 2025).